CXCL9 (C-X-C motif chemokine ligand 9)
Diseases named in the same sentence as CXCL9 in open-access papers (continued):
Sharing a sentence is not in itself a finding about the gene and the disease.
Chagas disease (7 papers, 2012 to 2024). A parasitic infection caused by Trypanosoma cruzi. "Genotype and allele frequencies for the CXCL9 rs10336 polymorphism in patients with Chagas disease." (PMID 23150742, 2012). "When compared to healthy controls, Chagas disease patients had higher circulating levels of IL-1-beta, CXCL9, and CXCL10 and lower levels of CCL5 than healthy subjects." (PMID 33262758, 2020). "Regarding chemokines, CXCL10 and CCL5 were increased in IND and CCC patients compared to CTRL, while CCL2, CXCL9 and CXCL8 were reduced in both clinical forms of Chagas disease compared to CTRL." (PMID 38390336, 2024). "Consistent with previous data, in addition to CXCL9, CXCL10 followed a similar trend, demonstrating higher levels in elderly patients with Chagas disease." (PMID 38139427, 2023). "Interestingly and in contrast with control individuals, levels of CXCL9 and CXCL10 continuously increased with age indicating that these two chemokines are strong markers of immunosenescence in the elderly with Chagas disease." (PMID 33262758, 2020). "Moreover, our data demonstrated that CXCL9 and CXCL10 increased in an age-dependent profile in Chagas disease patients." (PMID 32393333, 2020). "Our results demonstrated that Chagas disease patients had higher serum levels of CXCL9, CXCL10 and IL-1β and lower serum levels of CCL5 than non-infected subjects." (PMID 32393333, 2020).
endometriosis (7 papers, 2018 to 2022). The growth of functional endometrial tissue in anatomic sites outside the uterine body. "It is possible that the increased levels of MMP-9 in endometriosis result in cleavage and degradation of CXCL9 and CXCL10, causing decreased levels of these proteins." (PMID 30621017, 2019). "Endometriosis was also associated with elevated concentrations of IL-6, IL-10, and TGF-β1/2 as well as CCL20, CXCL8, CXCL9, and CXCL10." (PMID 34501240, 2021). "Concentrations of IL-6, IL-10, CCL2, CXCL8 and CXCL9 were significantly upregulated in the PF from women with endometriosis when compared to control women, whereas concentrations of other cytokines and chemokines were unaffected." (PMID 34360900, 2021). "The levels of some investigated cytokines and chemokines, such as IL-6, IL-10, CCL2, CXCL8, and CXCL9, were significantly increased in PF from patients with endometriosis as compared to control." (PMID 34360900, 2021). "Serum levels of AXIN1 and ST1A1 were increased in endometriosis compared with MC (p < 0.001) and healthy controls (p = 0.001), whereas CXCL9 levels were decreased." (PMID 30621017, 2019). "Endometriosis is widely known as an inflammatory condition and serum concentrations of the inflammatory proteins Axis inhibition protein 1 (AXIN1), Sulfotransferase Family 1A Member 1 (ST1A1) and C-X-C Motif Chemokine Ligand 9 (CXCL9) have been found to be altered in women with endometriosis." (PMID 35659226, 2022). "We also reported that the peritoneal fluid of patients with endometriosis showed significantly increased concentrations of CCL20, CXCL9, and CXCL10." (PMID 34501240, 2021). "The evaluation of chemokines showed that the peritoneal fluid from patients with endometriosis displayed significantly higher concentrations of CCL20, CXCL8, CXCL9, and CXCL10." (PMID 34501240, 2021). "PF from the women with endometriosis displayed significantly increased concentrations of CCL2, CXCL8 and CXCL9 as compared with the control subjects." (PMID 34360900, 2021). "There is increased expression of MMP-9 in endometrium and in peritoneal fluid in endometriosis, and MMP-9 cleaves CXCL9 at three different sites and degrades CXCL10." (PMID 30621017, 2019). "Previous studies have reported significantly lower concentrations of the closely related CXCL9 and CXCL10 (also called IP-10) in peripheral blood in endometriosis, in line with the present study." (PMID 30621017, 2019). "The results of the current study did not suggest that the localization of the endometriosis lesions is related to an altered profile of gut microbiota, in accordance with a recent study concerning potential plasma biomarkers for endometriosis, such as AXIN1, ST1A1, CXCL9, and OSM." (PMID 33660232, 2021). "The proteins AXIN1, ST1A1, CXCL9, and OSM, which showed the greatest differences between endometriosis and controls or symptoms, were not affected by the presence of IBS-like symptoms, localization of endometriosis lesions or hormonal treatment (data not shown)." (PMID 30621017, 2019).
heart failure (7 papers, 2017 to 2024). Inability of the heart to pump blood at an adequate rate to meet tissue metabolic requirements. "We discovered that 7 out of these 91 inflammatory factors influence heart failure, with 4 showing a significant causal relationship (CXCL9, IFN-γ, LIFR, UPA) and 3 being potentially related influencing factors (DNER, MMP-1, CD6)." (PMID 39726944, 2024). "Four of these factors were significantly causally related to the incidence of heart failure: CXCL9 and IFN-γ as promotive factors, and LIFR and UPA as potential protective factors." (PMID 39726944, 2024). "CXCL9 is a cytokine involved in chemotaxis and lymphocytic migration and has also been investigated as a potential biomarker of heart failure." (PMID 38248798, 2024). "We identified CXCL9, IFN-γ, LIFR, and UPA as potential inflammatory factors associated with heart failure through forward Mendelian randomization." (PMID 39726944, 2024). "Overall, there is substantial evidence linking increased circulating CXCL9 to the development of heart failure, and our Mendelian study further supports this perspective." (PMID 39726944, 2024). "Moreover, they also found elevated levels of CXCL9 in circulation in rat models of hypertensive myocardial hypertrophy or compensatory myocardial hypertrophy due to heart failure following myocardial infarction." (PMID 39726944, 2024). "In cardiovascular diseases, especially heart failure, the role of CXCL9 may lead to further damage and fibrosis in cardiac tissue, exacerbating heart failure." (PMID 39726944, 2024). "Altara R observed increased expression of CXCL9 in both distant and near-infarct areas of the heart in rats, maintaining high levels for up to 16 weeks post-myocardial infarction, suggesting a continuous role of CXCL9 in post-infarction heart failure." (PMID 39726944, 2024). "CXCR3 ligands such as CXCL9 and CXCL10 are considered as biomarkers for heart failure and other cardiovascular diseases." (PMID 35251049, 2022). "Its function can be regulated by cytokines, such as IFNγ and TNFα, and it has been proposed, together with CXCL9 and CXCL11, as a biomarker for heart failure and left ventricular dysfunction." (PMID 36364913, 2022). "Circulating CXCL9 and CXCL10 concentrations are also elevated in patients with heart failure, but to a lesser extent than what we observed in chronic Q fever patients." (PMID 28793883, 2017). "Furthermore, in a cohort study involving patients with hypertension combined with heart failure and a healthy control group, they reported higher levels of CXCR3 ligands, including CXCL9, in patients with left ventricular diastolic dysfunction." (PMID 39726944, 2024). "Additionally, they used the levels of CXCL9, CXCL10, and CXCL11 in their study to adjust the prediction in the heart failure model, finding that including CXCL9, CXCL10, and CXCL11 improved the prognosis prediction of heart failure." (PMID 39726944, 2024). "Investigators found significantly higher stem cell growth factor beta (SCGF beta), hepatocyte growth factor (HGF), monokine induced by interferon gamma (CXCL9), and macrophage inhibitory factor (MIF) in Chagas myocardiopathy patients with advanced heart failure compared to the control group." (PMID 38133693, 2023).
liver cirrhosis (7 papers, 2012 to 2025). "Inability to control infection leads to the recruitment of inflammatory infiltrates into the liver parenchyma by IFN-gamma-inducible CXCL9, -10 and -11 chemokines, which results in sustained liver damage and eventually in liver cirrhosis; however, fibrogenesis may also follow distinct paths." (PMID 22611419, 2012). "Among them, CCL5, CXCL9, CXCL12, LCK and CD24, which are thought to participate in the immune response, were identified as the most affected genes, suggesting a disruption of the immune response in liver cirrhosis." (PMID 34434654, 2021). "CXCL9 is known to promote the HCC invasion through PREX-2, therefore downregulation of the TLR4 and CXCL9/PREX-2 by probiotic bacteria could suppress the development of liver cirrhosis in the thioacetamide-treated rat model." (PMID 33807605, 2021).
lung disease (7 papers, 2015 to 2024). "CXCL9/MIG serves as an important antiviral defense, and plays an important role in the development or prevention of certain lung diseases." (PMID 35744838, 2022). "Our results suggest that inflammatory cytokines such as CXCL9/MIG, sIL-6R, and TARC could add moderate predictive value when evaluating smoking-related lung diseases." (PMID 35744838, 2022).
chronic hepatitis B (6 papers, 2013 to 2025). "These cases suggest that the increase in the serum levels of CXCL9, CXCL10, CXCL11, and CXCL13 were associated with attaining an HBsAg loss in children with chronic hepatitis B." (PMID 37206604, 2020).
chronic hepatitis C (6 papers, 2010 to 2022). "Several studies have demonstrated that both MIG/CXCL9 and IP-10/CXCL10 mRNA are elevated in experimental models of liver failure, and circulating levels of both chemokines are implicated in chronic hepatitis C." (PMID 24244295, 2013). "Serum CXCL9 concentrations correlated with the levels of fibrosis in chronic hepatitis C patients, and CXCL9 has been shown to exert anti-fibrotic effects in vitro and in vivo." (PMID 21886832, 2011). "Furthermore, CCL3, CCL4, CCL5, CXCL9, CXCL10 and CXCL11 were found to increase in both liver and peripheral blood during chronic hepatitis C in several studies." (PMID 29284412, 2017). "In acute HCV infection, the increases in CXCL9, CXCL10, and CXCL11 with ALT levels follow a similar pattern, while their intrahepatic expression is correlate with liver inflammation and fibrosis in chronic hepatitis C." (PMID 24976843, 2014).
co-infection (6 papers, 2012 to 2022). "Our study therefore suggests that in HIV patients with a low CD4+ T cell count, a HCMV co-infection generates an aggravated IFNγ response which thereby leads to the activation of the CXCL9/10/11-CXCR3 chemokine axis." (PMID 35538132, 2022). "In summary, viral coinfection during Mtb infection led to TB immunopathogenesis by downregulating the expression of the T cell migratory chemokines CXCL9/10 in infected lung tissues." (PMID 35672321, 2022). "Co‐infection with CHIKV induced higher splenic IFNγ levels that lead to high local levels of CXCL9 and CXCL10." (PMID 29113976, 2018). "This occurs through the induction of higher splenic IFNγ during co‐infection, leading to higher local levels of CXCL9 and CXCL10 that retains the CXCR3‐expressing CD8+ T cells in the spleen." (PMID 29113976, 2018). "To further demonstrate the causal relationship between IFNγ and CXCL9/CXCL10 induction in the co‐infected mice, we performed co‐infection in IFNγ−/− mice." (PMID 29113976, 2018). "In addition, the BCG-vaccinated group, which showed ameliorated exacerbation of pulmonary pathology induced by viral coinfection, already exhibited enhanced expression of CXCL9 at the time of LCMV Arm coinfection (14 days post Mtb infection)." (PMID 35672321, 2022).
coronary artery disease (6 papers, 2013 to 2024). "CXCL10 is the most extensively studied of the three chemokines in the clinical setting of ischemic heart disease; less is known about the role of CXCL9 and CXCL11." (PMID 30210493, 2018). "Interestingly, most of these pro-inflammatory genes like CCL5, CXCL10, CXCL9, CTSK, and CD14 have been previously reported to be elevated in the serum of patients with coronary artery diseases." (PMID 35488341, 2022).
Crohn disease (6 papers, 2012 to 2025). A gastrointestinal disorder characterized by chronic inflammation involving all layers of the intestinal wall, noncaseating granulomas affecting the intestinal wall and regional lymph nodes, and transmural fibrosis. "Intron 1 of the CXCL9 gene (rs2276886) polymorphism may be closely related to pediatric Crohn's disease." (PMID 28589131, 2017). "Nevertheless, the top signal identified for AD (circulating MIG [CXCL9] level [NSNP = 2; ORIVW 1.23; 95% CI 1.06–1.42; pIVW = 0.007]) also was a suggestive causal biomarker for Crohn disease (NSNP = 2; ORIVW 0.73; 95% CI −0.62 to 0.86; pIVW = 1.3 × 10−4)." (PMID 36384659, 2023). "Similarly, Cxcl9 expression is up-regulated in UC, and Cxcl5 is one of the main chemokines expressed in intestinal tissue of Crohn’s disease patients." (PMID 33864170, 2021). "However, colocalization did not suggest a common causal SNP for AD and Crohn disease within the genomic region (±50 kb from the MIG coding gene CXCL9) (posterior probability [PP.H4] = 0.001; eFigure 7, links.lww.com/WNL/C487)." (PMID 36384659, 2023).
dry eye (6 papers, 2013 to 2024). "The tear levels of CXCL9, -10 and -11 were 1,148 +/- 1,088, 24,338 +/- 8,706, and 853 +/- 334 pg/mL, in dry eye, and only 272 +/- 269, 18,149 +/- 5,266, and 486 +/- 175 pg/mL in controls respectively." (PMID 26605353, 2014). "The tear chemokines which have been implicated in dry eye are CX3CL1, CXCL10, CCL4/MIP-1beta, CCL3/MIP-1alpha, CCL5/RANTES, CXCL9, -10, and -11." (PMID 26605353, 2014). "It is known that elevated concentrations of CXCL9, -10, -11 have been detected in the tears of dry eye patients." (PMID 24223818, 2013). "Additionally, there have been reports of increased expression levels of CXCL9/10/11 in the conjunctival epithelium of pSS patients with xerophthalmia." (PMID 38900301, 2024). "Increased production of CXCR3 and CXCL-9, -10, and -11 have been observed in the ocular surface and increased frequency of CXCR3+ and CCR5+ T cells has been detected in draining lymph nodes of mice with experimental dry eye induced by subjecting them to desiccating stress (DS)." (PMID 24223818, 2013). "Also, increased levels of CXCR3 ligands—CXCL9, CXCL-10 andCXCL-11—were detected in tears of patients with pSS compared with those of patients with non-Sjögren’s dry eye." (PMID 37893153, 2023).
fibrosis (6 papers, 2015 to 2025). the formation of excess fibrous connective tissue in an organ or tissue in a reparative or reactive process. "Increased anti‐inflammatory cytokine IL‐10 and CXCL9 levels were observed, resulting in lower lung hydroxyproline content and Ashcroft fibrosis score." (PMID 39582275, 2024).
head and neck cancer (6 papers, 2018 to 2025). A primary or metastatic malignant neoplasm affecting the head and neck. "We evaluated RNA-seq data from TCGA and found K17 expression level was inversely correlated with that for CD8A and CXCL9 in a cohort of 513 patients with head and neck cancer." (PMID 31968015, 2020). "In this study, we analyzed the immune regulatory properties of EGFR signaling in head and neck cancer cells and showed that it suppresses type 1 cytokine-induced expression of CCL2, CCL5, CXCL9, CXCL10 and IL-6 while promoting the expression of IL-1β." (PMID 30192802, 2018). "In vivo, cetuximab treatment enhanced the serum levels of CXCL9 and CXCL10 in patients with head and neck cancer." (PMID 30192802, 2018).
HIV-1 infection (6 papers, 2018 to 2023). The type species of lentivirus and the etiologic agent of acquired immunodeficiency syndrome (AIDS). "In the Swiss HIV Cohort, we found that CXCL10, CCL2 and, to a lesser extent, CXCL9 transcripts were significantly upregulated during untreated HIV-1 infection." (PMID 37601355, 2023). "We identified a cluster of IRPs (cluster 7), including CXCL11, CXCL9, TNF, CXCL10, and IL18, which was closely associated with T cell dysregulation during chronic HIV-1 infection." (PMID 36408648, 2023). "A previous study demonstrated that CXCL9, CXCL10, and CXCL11 levels can predict HIV-1 disease progression during primary HIV-1 infection." (PMID 36408648, 2023). "A panel of plasma CXCL9, CXCL10, and CXCL11 measured during primary HIV-1 infection could predict long-term HIV disease prognosis in an MSM group and has potential as a novel biomarker in the clinic." (PMID 31836011, 2019). "Many studies have previously reported a correlation between the observed increase in the production of pro-inflammatory cytokines IL-1β, IL-6, IL-18 and TNF-α; and IFN inducible chemokines CXCL9, CXCL10 and CXCL11 during the course of HIV-1 infection and the up regulation of HIV-1 replication." (PMID 29373606, 2018).
hypersensitivity pneumonitis (6 papers, 2005 to 2024). Hypersensitivity pneumonitis (HP) is a pulmonary disease with symptoms of dyspnea and cough resulting from the inhalation of an antigen to which the subject has been previously sensitized. "Lower serum CXCL9 in patients with hypersensitivity pneumonitis (HP) is associated with a more significant decline in vital capacity, suggesting that CXCL9 is a crucial predictor of lung function deterioration similar to IPF." (PMID 39768150, 2024).
Hypertension (6 papers, 2015 to 2025). The presence of chronic increased pressure in the systemic arterial system. "Moreover, these patients presented increased counts of immunosenescent CD8+ T cells, indicating that CXCL9 could play a role in immune dysregulation and vascular inflammation in hypertension." (PMID 40977717, 2025). "Beyond the liver, the CXCL9/CXCR3 axis also appears to be involved in renal and vascular homeostasis, with implications for hypertension and systemic inflammation." (PMID 40977717, 2025).
interstitial lung disease (6 papers, 2020 to 2026). A diverse group of lung diseases that affect the lung parenchyma. "Candidate biomarkers CXCL9, GDF15, and vWF have previously been shown to correlate with global JDM activity, and WFDC2 and TNFSF13 have been associated with interstitial lung disease in DM." (PMID 39529136, 2024).
myositis (6 papers, 2020 to 2025). "Previous studies have also shown elevated muscle levels of numerous cytokines associated with type 1 inflammation, including CCL5, CXCL9, CXCL10, CXCL11, IFNG, and TNF in IBM patients compared to various myositis and non-myositis controls." (PMID 40034760, 2025). "Similar elevations of cytokines associated with type 1 inflammation, including CXCL9, CXCL10, IFN-γ, IL-12, and TNF have been demonstrated at the protein level in serum of IBM patients versus non-myositis controls." (PMID 40034760, 2025). "Of interest, CXCR3 ligands, CXCL9 and CXCL10, are increased in the serum of Jo1+ and SRP+ myositis patients, and CXCL10 is a validated disease activity biomarker for juvenile dermatomyositis." (PMID 35371068, 2022). "The expression of the three ligands of CXCR3 (CXCL9, CXCL10, and CXCL11) is significantly increased in various diseases such as interstitial cystitis, ulcerative colitis, and myositis, and previous studies found that blocking CXCL10 can reduce the degree of the damage of these diseases." (PMID 35036436, 2022).
squamous cell carcinoma (6 papers, 2022 to 2026). A carcinoma arising from squamous epithelial cells. "Some studies have reported that CXCL9 up-regulation in HNC squamous cell carcinoma contributes to worse disease outcomes." (PMID 38067251, 2023). "A recent study reported that CXCL9 and SPP1 are very rarely expressed in the same monocyte, and that the balance of CXCL9+ vs SPP1+ TAMs predict patient outcome for squamous cell carcinomas of the head and neck." (PMID 40176808, 2025). "To investigate the anti-tumor effects of the IFN-inducible chemokines CXCL9, CXCL10, and CXCL11, we generated a cell line stably expressing these IFN-inducible chemokines using the mouse squamous cell carcinoma cell line SCCVII." (PMID 37218983, 2023).